MIB2 (MIB E3 ubiquitin protein ligase 2)
Diseases named in the same sentence as MIB2 in open-access papers (continued):
Sharing a sentence is not in itself a finding about the gene and the disease.
skin inflammation (1 paper, 2024). "Here we show that MIB2 is a novel regulator of skin inflammation in the context of the cpd mutation." (PMID 38156288, 2024). "This highlights the distinct roles of these closely related proteins, emphasizing the unique contribution of MIB2 in regulating skin inflammation-associated cpdm-linked dermatitis." (PMID 38156288, 2024). "Loss of MIB2 in the context of the cpd mutation reduced the abundance of G-CSF in the skin that correlated with enhanced dermatitis severity, suggesting G-CSF acts to promote wound healing in this inflammatory dermatitis model." (PMID 38156288, 2024). "Collectively, our proteomic analysis unravels an intricate network of protein expression changes influenced by MIB2 deficiency in the context of cpdm-driven dermatitis." (PMID 38156288, 2024). "Consistent with our hypothesis, deletion of MIB2 accelerated the progression of dermatitis caused by mutation of Sharpin when compared to a cohoused cohort of SharpincpdmMib2+/+ animals scored at the same time." (PMID 38156288, 2024). "MIB2 is required for the efficient production of these chemokines in the cpd skin, but if or how changes in the levels of these molecules modulate dermatitis remains to be determined." (PMID 38156288, 2024). "To identify how MIB2 might alter the proteomic landscape to limit progressive dermatitis, we performed an unbiased mass-spectrometry-based analysis of skin tissue lysates." (PMID 38156288, 2024). "However, reducing the E3 ubiquitin ligase activity of MIB2 with the F920A mutation did not impact dermatitis severity." (PMID 38156288, 2024). "The distinct skin phenotype, including exacerbated dermatitis and excessive epidermal hyperplasia observed in the absence of MIB2 in the context of the Sharpin cpd mutation is noteworthy, particularly given that no exacerbation of other cpdm-driven phenotype was observed." (PMID 38156288, 2024). "Interestingly, MIB2 may have disease-specific functions in regulating skin inflammation." (PMID 38156288, 2024). "Surprisingly, the role of MIB2 in limiting skin inflammation is independent of its known pro-survival function and E3 ligase activity." (PMID 38156288, 2024). "Surprisingly, our data reveal that the regulatory function of MIB2 in skin inflammation is independent of its role in cell death or E3 ligase activity." (PMID 38156288, 2024). "These lesions occur with rapid onset (1–3 days) relative to visible dermatitis in Sharpincpdm animals and were not impacted upon deletion or inactivation of MIB2 (data not shown)." (PMID 38156288, 2024). "Tumour necrosis factor (TNF) and caspase-8-driven cell death causes the pathogenesis of Sharpincpdm mice; however, the role of mind bomb 2 (MIB2), a pro-survival E3 ubiquitin ligase involved in TNF signaling, in skin inflammation remains unknown." (PMID 38156288, 2024). "This indicates that augmented cell death in the absence of Mib2 was not occurring in the skin of SharpincpdmMib2−/− mice and, therefore, in this context MIB2 deletion does not restrain dermatitis in Sharpincpdm animals by inhibiting TNF-induced and RIPK1-mediated cell death." (PMID 38156288, 2024). "More broadly, eosinophils aid wound healing and epithelial remodeling and the accelerated dermatitis we observe in the absence of MIB2 could be explained by the reduction in eotaxin and a subsequent defect in eosinophil recruitment." (PMID 38156288, 2024).
steatosis (1 paper, 2025). Increased lipid within the cytoplasm of cells. "We have discovered a biological axis, Mib2‐Runx2‐Hmgcs2, in the regulation of cardiac steatosis in HFpEF, providing a promising therapeutic strategy for cardiometabolic HFpEF." (PMID 40159625, 2025). "This hypothesis is supported by our results that restoration of Mib2 exacerbated cardiac dysfunction and lipid storage in the heart, which was further verified by NRVMs that Mib2 overexpression exacerbates cardiomyocyte steatosis in vitro assay." (PMID 40159625, 2025).
Stroke (1 paper, 2020). Sudden impairment of blood flow to a part of the brain due to occlusion or rupture of an artery to the brain. "Microglial Mib2 knockout protects ischemia-induced brain injury, suggesting that Mib2 might be a potential therapeutic target in stroke treatment." (PMID 32489699, 2020). "Since Mib2 is upregulated in animal models of tMCAo and plays an important role in the peripheral immune system, we speculated that Mib2 might play an important role in regulating microglial activation during stroke." (PMID 32489699, 2020). "Here, we found that Mib2 promotes NF-κB signaling in microglia by targeting the IKK complex, thus providing additional evidence for the detrimental role of NF-κB signaling in stroke." (PMID 32489699, 2020).
triple-negative breast carcinoma (1 paper, 2018). An invasive breast carcinoma which is negative for expression of estrogen receptor (ER), progesterone receptor (PR), and human epidermal growth factor receptor 2 (HER2). "Moreover, CRISPR/Cas9-mediated deletion of MIB1 and MIB2 also sensitized the triple-negative breast cancer cell line MDA-MB-231 to TNF/TAK1i in a RIPK1-dependent manner." (PMID 29642005, 2018).
cancer (10 papers, 2018 to 2025). A tumor composed of atypical neoplastic, often pleomorphic cells that invade other tissues. "Mind bomb homolog 2 (MIB2) regulates the transportation of PD-L1 to the cell membrane in cancer cells, facilitating PD-1/PD-L1 binding." (PMID 39223632, 2024). "Herein, we showed that mind bomb homolog 2 (MIB2) is required for PD-L1 transportation from the trans-Golgi network (TGN) to the plasma membrane of cancer cells." (PMID 36719382, 2023). "The public databases were used to compare the expression level of MIB2 in cancer and non-cancer tissue." (PMID 37436668, 2023). "Unpublished truncating variants in two genes under-expressed in cancer [CEACAM1:c.553_554insAGGC; p.(Leu185Glnfs∗26), and MIB2: c.153C > A; p.(Cys51∗)] were also inherited." (PMID 30233642, 2018). "Among which, the biological function of Mib2 was reported primarily in cancer research." (PMID 40159625, 2025). "Because pharmacological inhibitors of IAPs are in clinical testing, our data suggest that targeting the MIB2 Ub ligase might improve the efficacy of SMs for the treatment of cancer." (PMID 29642005, 2018). "MIB2 is a pro-survival E3 ubiquitin ligase that cooperates with the IAPs and TAK1 to limit the pro-apoptotic activities of RIPK1, thereby reducing TNF-mediated cancer cell death." (PMID 38156288, 2024).
tumor (7 papers, 2014 to 2025). "Suppression of MIB2 expression in various tumor cells led to same effects as loss of FAT1 expression, including a decrease in YAP and TAZ ubiquitination, and degradation as well as an increase in YAP/TAZ protein levels and expression of YAP/TAZ target genes." (PMID 40478800, 2025). "Our study identifies a mechanism by which YAP/TAZ levels are kept low through FAT1/MIB2-mediated protein degradation and shows that tumor progression resulting from mutation of tumor suppressor FAT1 involves loss of MIB2-dependent degradation of YAP and TAZ." (PMID 40478800, 2025). "We found that the depletion of MIB2 in B16-F10 cells caused significant tumor regression and prolonged survival in immunocompetent C57BL/6 syngeneic mice but not in immunodeficient NOD/SCID IL2rgnull (NSG) mice." (PMID 36719382, 2023). "MIB2 deficiency led to fewer PD-L1 proteins on the tumor cell surface and promoted antitumor immunity in mice." (PMID 36719382, 2023). "However, in all tumor cells studied by us, loss of MIB2-mediated YAP/TAZ degradation appeared to be a requirement for increased tumor progression in the absence of FAT1 function." (PMID 40478800, 2025). "Loss of either FAT1 or MIB2 significantly elevates YAP/TAZ protein levels, enhances their transcriptional activity, and promotes tumor cell proliferation in both in vitro and in vivo models." (PMID 40478800, 2025). "The present study demonstrates that MIB2-mediated YAP/TAZ degradation plays a crucial role in the tumor-suppressive function of FAT1." (PMID 40478800, 2025). "It controls Yap/Taz protein degradation to inhibit angiogenesis in tumors, and the ubiquitination of PD‐L1 by Mib2 is required for tumour cell immune evasion." (PMID 40159625, 2025). "When analyzing the interactome of the cytoplasmic part of FAT1 in tumor cells, we identified the E3 ubiquitin ligase Mind Bomb-2 (MIB2) as an interaction partner." (PMID 40478800, 2025). "This is supported by our in vivo data demonstrating that loss of FAT1 as well as of MIB2 increased YAP/TAZ protein levels and tumor growth of Hela cells as well as of HNSCCs and that FAT1-mediated reduction in tumor progression depended on MIB2." (PMID 40478800, 2025). "To investigate the role of MIB2, we performed siRNA-mediated knockdown in multiple tumor cell lines." (PMID 40478800, 2025). "CD8+ T cell depletion restored the growth of MIB2-KO B16-F10 tumors and significantly increased tumor burden, reinforcing that the antitumor effect partly depends on T cells." (PMID 36719382, 2023). "We demonstrate a positive correlation between MIB2 expression and the membrane abundance of PD-L1 in tumor cells in NSCLC tissues." (PMID 36719382, 2023). "Of the 93 tumor specimens, 42 showed low MIB2 expression, 36 of which also showed low PD-L1 membrane staining." (PMID 36719382, 2023). "In line with the scRNA-Seq data, IF staining results revealed that MIB2 knockdown increased the tumor-infiltrated CD8+ T cell population and granzyme B release in B16-F10 tumors from C57BL/6 syngeneic mice." (PMID 36719382, 2023). "We found that the expression of both total MIB2 and membrane PD-L1 in the tumor epithelial region exhibited a predictive accuracy of 54.5% for PR." (PMID 36719382, 2023). "Reintroduction of MIB2 in MIB2-KO A375 cells restored PD-1 binding and impaired T cell–mediated tumor cell killing in vitro." (PMID 36719382, 2023). "Consistently, the loss of MIB2 in MC38 and LLC1 cells only restricted tumor development and improved survival in C57BL/6 mice." (PMID 36719382, 2023). "In summary, we revealed what we believe to be a new mechanism of immunosuppression in tumor cells through MIB2-mediated ubiquitination of PD-L1, which enables its translocation to the plasma membrane." (PMID 36719382, 2023). "MIB2 KO delayed tumor development in both B16-F10 tumors with IgG isotype control antibody (IgG2A) treatment." (PMID 36719382, 2023).
tumor (continued). "Thus, also under in vivo conditions, was the ability of FAT1 to increase YAP/TAZ protein degradation and to function as a tumor suppressor dependent on MIB2." (PMID 40478800, 2025). "Similarly, Hela cells or HNSCCs with suppressed MIB2 expression resembled FAT1 defective tumor cells showing faster proliferation in vitro as well as increased tumor growth in vivo compared to control cells." (PMID 40478800, 2025). "Given that Notch can be either oncogenic or tumor-suppressive depending on the cellular context in various tumors including HNSCC, it is conceivable that loss of FAT1 affects Notch signaling in tumor cells through altered localization of MIB2." (PMID 40478800, 2025). "Notably, MIB2 KO significantly enhanced the antitumor efficacy of PD-1 mAb, in that tumor growth was restricted and survival was improved." (PMID 36719382, 2023). "We determined whether MIB2 knockdown affected T cell–mediated antitumor immune activity by characterizing the subpopulations of tumor-infiltrating T cells." (PMID 36719382, 2023). "Furthermore, MIB2 KO enhanced T cell–mediated tumor cell killing in vitro." (PMID 36719382, 2023). "In this study, we found that mind bomb homolog 2–mediated (MIB2-mediated) K63-linked ubiquitination of PD-L1 facilitates its translocation from the trans-Golgi network (TGN) to the plasma membrane through RAB8-regulated exocytosis, ultimately promoting immune evasion and tumor progression." (PMID 36719382, 2023). "While control Hela cells injected into NOG mice lead to tumor formation after 14 days, Hela cells with knock-down of FAT1 or MIB2 developed visible tumors as early as 9 days after injection." (PMID 40478800, 2025). "In tumor cells, FAT1 interacts with the E3 ligase MIB2 to facilitate the ubiquitin-dependent degradation of YAP/TAZ." (PMID 40478800, 2025). "Similar to Hela tumor cells with suppressed expression of FAT1 and MIB2, we also saw increased tumor growth in the HNSCC CAL27 with suppressed FAT1 and MIB2 expression after subcutaneous injection of cells into NOG mice." (PMID 40478800, 2025). "The antitumor potential of PD-1 mAb was further enhanced in MIB2-KO MC38 tumors, in that the in vivo tumor development was substantially impaired, and 5 of 15 tumor-bearing mice were tumor-free for 50 days." (PMID 36719382, 2023). "Treatment with PD-1 mAb markedly inhibited the growth of MIB2 WT MC38 tumors, and 3 of 15 of the tumor-bearing mice survived for more than 50 days after tumor inoculation." (PMID 36719382, 2023). "Our data highlights a novel interacting partner of CYLD, MIB2, that influences Notch signalling and furthermore the potential therapeutic utility of γ-secretase inhibition in CYLD defective tumours." (PMID 25565632, 2014). "While we found in all tested tumor cells that YAP/TAZ protein levels were regulated by FAT1 in a MIB2-dependent manner, not all cells showed CAMK2-dependent nuclear translocation." (PMID 40478800, 2025). "Since we recently described that in endothelial cells the intracellular domain of FAT1 interacts with the E3-ligase MIB2 to control YAP/TAZ protein degradation, we tested whether this interaction also occurs in tumor cells." (PMID 40478800, 2025). "We then suppressed expression of FAT1 or MIB2 using lentiviral transfer of shRNA directed against FAT1 or MIB2 in Hela cells and in the FAT1-expressing HNSCC CAL27 and analyzed the growth of tumor cells in vivo after subcutaneous injection." (PMID 40478800, 2025). "Our findings demonstrate that nonproteolytic ubiquitination of PD-L1 by MIB2 is required for its transportation to the plasma membrane and tumor cell immune evasion." (PMID 36719382, 2023). "Unlike other E3 ligases, MIB2 does not reduce the total protein levels of PD-L1, nor does it appear to affect the intrinsic functions of PD-L1 in tumor cells." (PMID 36719382, 2023). "Without MIB2, PD-L1 within tumor cells cannot be translocated to the plasma membrane for its extrinsic function in binding PD-1 and evading immunity." (PMID 36719382, 2023).
tumor (continued). "In addition, mind bomb homolog 2 (MIB2) catalyzes the ubiquitination of PD-L1 at the K63 linkage, but not its degradation, and promotes tumor immune escape." (PMID 39048965, 2024). "To investigate whether suppression of MIB2 expression mimics the effect of a loss of FAT1 on tumor cell growth, we suppressed expression of FAT1 or MIB2 using siRNA in Hela cells as well as in HNSCCs lacking or expressing FAT1 followed by evaluation of cell growth and EdU incorporation." (PMID 40478800, 2025). "Mechanistically, MIB2 catalyzed nonproteolytic K63-linked ubiquitination of PD-L1, facilitating PD-L1 trafficking through Ras-associated binding 8–mediated (RAB8-mediated) exocytosis from the TGN to the plasma membrane, where it bound PD-1 extrinsically to prevent tumor cell killing by T cells." (PMID 36719382, 2023). "The increase in tumor growth in the absence of FAT1 and MIB2 was again accompanied by increased expression of YAP/TAZ target genes as well as of YAP/TAZ protein." (PMID 40478800, 2025). "The increased tumor growth of Hela cells lacking FAT1 and MIB2 was accompanied by increased expression of YAP/TAZ target genes and increased levels of YAP/TAZ protein in the tumors." (PMID 40478800, 2025). "MIB2 KO markedly restricted tumor growth and improved survival rate when combined with either PD-L1 or CTLA4 mAb, but no mice survived more than 50 days after tumor inoculation." (PMID 36719382, 2023). "However, tumor development and mouse survival rate appeared to be comparable in NSG mice regardless of MIB2 status." (PMID 36719382, 2023).
infection (2 papers, 2012 to 2023). The state of being infected such as from the introduction of a foreign agent such as serum, vaccine, antigenic substance or organism. "Even if the level of circMIB2 in the host is low, it is not a concern because we have demonstrated that artificially increasing the levels of circMIB2 or MIB2-134aa protein effectively alleviates the infection caused by SCRV or V. anguillarum in the host." (PMID 37652905, 2023). "Sendai virus-induced IRF3 and TBK1 phosphorylation were dramatically reduced in MIB1/MIB2 double deficient MEFs compared to control mib1f/f MEFs in early infection." (PMID 23028469, 2012). "Furthermore, we found that silence of MIB2 significantly inhibited SCRV replication after SCRV infection, and MIB2 overexpression significantly promoted SCRV replication." (PMID 37652905, 2023). "Overexpressing MIB2 significantly inhibited ISG15 protein levels, while knocking it boosted ISG15 protein expression during SCRV infection." (PMID 37652905, 2023). "After knocking down MIB2, the CPE (cytopathic effect) was significantly reduced under SCRV infection conditions, while transfection with circMIB2 resulted in a significant increase in CPE." (PMID 37652905, 2023).
cardiovascular diseases (1 paper, 2025). "This discovery not only broadens the understanding of the biological functions of Mib2 but also provides a new potential therapeutic target for cardiovascular diseases." (PMID 40159625, 2025).
skin disorder (1 paper, 2024). Any deviation from the normal structure or function of the skin or subcutaneous tissue that is manifested by a characteristic set of symptoms and signs. "While MIB2 mutations have not been linked to inflammatory skin lesions in humans, further investigation into the function of MIB2 in other genetic perturbations and skin disorders holds promise for gaining insights into skin homeostasis and related conditions." (PMID 38156288, 2024).
MIB2 also shares sentences with these, for which no sentence is quoted: alcohol addiction (1 paper); atherosclerosis (1); brain injury (1); brain tumors (1); ciliopathy (1); colorectal carcinoma (1); heart failure (1); Intellectual disability (1); leiomyoma (1); MALT lymphoma (1); Ménétrier disease (1); spina bifida cystica (1); type 1 diabetes (1).